ZNF706 (zinc finger protein 706)
Description:
Transcription repressor involved in the exit of embryonic stem cells (ESCs) from self-renewal (By similarity). Acts by repressing expression of KLF4 (By similarity). Required for Wnt signaling activation.
Synonyms: HSPC038; PNAS-113; PNAS-106
Tractability: Antibody: the Human Protein Atlas places it where antibodies can reach. PROTAC: ubiquitination databases record sites on it.
Gene: Protein-coding gene on chromosome 8 (101,177,720 to 101,207,085, reverse strand). Ensembl gene ENSG00000120963.
Subcellular location: Cytoplasm; Nucleus
Subcellular location (Human Protein Atlas): Plasma membrane
Pathways (Reactome):
Gene expression (Transcription): Generic Transcription Pathway
Gene Ontology:
Biological process: negative regulation of DNA-templated transcription; negative regulation of stem cell population maintenance
Cellular component: cytoplasm; nucleus
Genetic constraint (gnomAD): Loss-of-function variants: 4 observed, 9.07 expected, observed/expected ratio (o/e) 0.44, 90% interval 0.22 to 1.01. That is too few expected variants to judge how well the gene tolerates losing a copy. Missense variants: 27 observed, 89.15 expected, observed/expected ratio (o/e) 0.3, 90% interval 0.22 to 0.42. Synonymous variants: 28 observed, 26.2 expected, observed/expected ratio (o/e) 1.07, 90% interval 0.79 to 1.47.
Homologues: Orthologues: chimpanzee ZNF706 (100% identical), dog ZNF706 (100% identical), guinea pig ZNF706 (100% identical), macaque ZNF706 (100% identical), mouse Zfp706 (100% identical), pig ZNF706 (100% identical), rabbit ZNF706 (100% identical), rat Zfp706 (100% identical), tropical clawed frog znf706 (87% identical), zebrafish znf706 (82% identical), Caenorhabditis elegans K10B3.1 (67% identical), Caenorhabditis elegans znf-706 (67% identical), and 2 more.
Diseases named in the same sentence as ZNF706 in open-access papers:
ZNF706 is named in the same sentence as 12 diseases in open-access papers, as found by Europe PMC text mining. Sharing a sentence is not in itself a finding about the gene and the disease. The quoted sentences say what the papers report.
laryngeal carcinoma (2 papers, 2013 to 2017). Carcinoma that arises from the laryngeal epithelium. "The ZNF706 gene encodes a protein that belongs to the zinc finger family of proteins and was found to be highly expressed in laryngeal cancer, making the structure and function of ZNF706 worthy of investigation." (PMID 24060497, 2013). "However, it was observed that ZNF706 gene has a sex-specific gene expression pattern in human lymphoblastoid cell lines, and was found to be highly expressed in laryngeal cancer." (PMID 24060497, 2013). "However, zinc finger protein 706 (ZNF706) is also highly expressed in laryngeal cancer." (PMID 28450890, 2017).
prostate carcinoma (2 papers, 2018 to 2024). A carcinoma that arises from epithelial cells of the prostate gland. "Selected ARA-lincRNAs are neighbors of protein-coding genes WDR5, ZNF706, TFRC, and FLNA, which have been described as up-regulated in prostate cancer, and of CENPH and RAB11FIP3, which have been shown to play a role in many other types of cancer." (PMID 29875794, 2018).
hepatocellular carcinoma (1 paper, 2024). A malignant tumor that arises from hepatocytes. "Clinically, ZNF706 expression was elevated in hepatocellular carcinoma (HCC), and high ZNF706 expression was associated with unfavorable survival in HCC patients." (PMID 38862581, 2024). "In the present study, we identified the biological roles and regulatory mechanisms of ZNF706, a novel zinc finger nuclear protein, in advanced progression of human hepatocellular carcinoma." (PMID 38862581, 2024).
Infertility (1 paper, 2021). "The impaired function of oxidative phosphorylation could be the predominant reason for crossbred bull infertility; and significant downregulation of ZNF706, CRISP2, TNP2, and TNP1 genes indicates that they could serve as potential biomarkers for fertility in crossbred bulls." (PMID 34041237, 2021).
liver cancer (1 paper, 2024). An epithelial or non-epithelial malignant neoplasm that arises from the liver. "Collectively, these observations suggest that ZNF706 is overexpressed in liver cancer and is associated with poor survival in HCC patients." (PMID 38862581, 2024). "Collectively, our data demonstrate that ZNF706 is a potential oncogene in liver cancer and functions as a ferroptosis regulator by modulating SLC7A11 expression, constituting a potential therapeutic target for HCC." (PMID 38862581, 2024). "Accordingly, the inhibitory effect from ZNF706 knockdown was related to the significant inhibition of proliferation in the four liver cancer cell lines, as determined by soft agar assays." (PMID 38862581, 2024). "Moreover, a colony formation assay was performed, and we observed that ZNF706 knockdown noticeably suppressed the anchorage-dependent growth of these four liver cancer cell lines." (PMID 38862581, 2024). "Moreover, analysis of mRNA expression data obtained from the HCC datasets GSE3500, GSE14520, and GSE6764 in the Gene Expression Omnibus (GEO) database demonstrated that ZNF706 was obviously overexpressed in liver cancer." (PMID 38862581, 2024). "Notably, ZNF706 amplification occurred in approximately 8% of the liver cancer cases with genetic abnormalities." (PMID 38862581, 2024). "Moreover, the copy number of ZNF706 was analyzed in The Cancer Genome Atlas (TCGA) and the GSE32649 dataset was found to be significantly increased in liver cancer." (PMID 38862581, 2024).
cancer (6 papers, 2011 to 2024). A tumor composed of atypical neoplastic, often pleomorphic cells that invade other tissues. "Therefore, our findings support the idea that inhibition of ZNF706 sensitizes cancer cells to Sorafenib." (PMID 38862581, 2024). "Moreover, it represents the first step towards a future customized ZNF706 peptide that could act on cellular signaling networks and establishing the relationship between ZNF706 and diseases such as cancer." (PMID 24060497, 2013). "Moreover, it represents the first step towards a future customized ZNF706 peptide that could act on cellular signaling networks and establishes the relationship between ZNF706 and diseases such as cancer." (PMID 24060497, 2013). "Therefore, we sought to determine whether knockdown of ZNF706 sensitizes cancer cells to Sorafenib." (PMID 38862581, 2024).
tumor (2 papers, 2018 to 2024). "Previous studies on the functional annotation of ZNF706 have been reported to be relatively scarce, and its role and mechanism in tumor progression are even more lacking." (PMID 38862581, 2024).
ZNF706 also shares sentences with these, for which no sentence is quoted: breast carcinoma (2 papers); bladder cancer (1); head and neck cancer (1); non-small cell lung carcinoma (1); ovarian carcinoma (1).